ZEB1 (zinc finger E-box binding homeobox 1)
Diseases named in the same sentence as ZEB1 in open-access papers (continued):
Sharing a sentence is not in itself a finding about the gene and the disease.
renal cell carcinoma (10 papers, 2015 to 2025). "Zhang et al28 found that Jab1 promotes epithelial‐mesenchymal transition by inhibiting ZEB1 degradation, and Jab1 overexpression is correlated with poor OS in patients with renal cell carcinoma." (PMID 33550701, 2021). "LncRNA SCAMP1 has been reported to regulate ZEB1/JUN axis in renal cell carcinoma." (PMID 35992869, 2022). "Therefore, lncRNA SCAMP1 enhanced progression of renal cell carcinoma via regulation of autophagy and miR-429/ZEB1/JUN axis under oxidative stress." (PMID 35992869, 2022). "In renal cell carcinoma (RCC), miR-429 typically reduces the expression of ZEB1 to suppress RCC progression." (PMID 32664703, 2020). "The study of Chen H shown that ZEB1 up-regulates the expression of centrosome protein 55 and affects the migration, invasion, and EMT of renal cell cancer cells." (PMID 38693503, 2024). "Other EMT regulators, such as Zeb1, Zeb2, and TCF-3, have been reported to be upregulated in pVHL-null renal cell carcinoma in which HIF-1α is constitutively overexpressed." (PMID 30696468, 2019). "However, a newly identified mechanism of IFIT5 is regulation of the turnover of tumor suppressor microRNAs (miRNAs), including miR-363 and miR-128, resulting in increased expression of transcription factors of EMT such as slug and ZEB1, thereby enhancing invasion in renal cell carcinoma (RCC)." (PMID 31921891, 2019). "Moreover, miR-429 targets both ZEB1 and JUN in renal cell carcinoma cells." (PMID 35992869, 2022).
cutaneous melanoma (9 papers, 2020 to 2025). A primary melanoma arising from atypical melanocytes in the skin. "In addition, ZEB1 mutation was highly related to overall survival in cutaneous melanoma, while CP may be associated with tumor progression." (PMID 35232428, 2022). "For skin melanoma, it has recently been shown that ZEB1 controls a lineage-specific transcriptional program and phenotypic transition." (PMID 41226394, 2025). "Survival analysis in cutaneous melanoma patients showed that high TWIST1 and ZEB1 expression was associated with a shorter metastasis-free survival." (PMID 35682684, 2022). "Normal cutaneous melanocytes have a high expression of SNAI2 and ZEB2 and a low expression of ZEB1 and TWIST1, while malignant cutaneous melanomas have low SNAI2 and ZEB2 and high ZEB1 and TWIST1." (PMID 35682684, 2022). "Since many researchers consider high ZEB1 as a negative factor for both skin melanoma and UM, various attempts have been made to regulate ZEB1 and validate it as a therapeutic target." (PMID 41226394, 2025). "In addition, the expression of CD47 was positively correlated with ZEB1 in 178 PDAC and 103 skin cutaneous melanoma (SKCM) patients." (PMID 32536914, 2020).
mantle cell lymphoma (9 papers, 2015 to 2025). Mantle cell lymphoma is a rare form of malignant non-Hodgkin lymphoma affecting B lymphocytes in the lymph nodes in a region called the ``mantle zone''. "For example, Wnt/β-Catenin signaling regulates ZEB1 expression in mantle cell lymphoma, and silencing ZEB1 suppresses cell proliferation and xenograft growth, and increases gemcitabine sensitivity of mantle cell lymphoma cells." (PMID 33436545, 2021). "In mantle cell lymphoma patients, high expression levels of ZEB1 were correlated with shorter overall survival." (PMID 32046309, 2020). "In contrast to T-cell malignancies, ZEB1 expression is increased in B-cell malignancies, specifically Mantle Cell Lymphoma (MCL) and Diffuse B Cell Lymphoma (DLBCL)." (PMID 37600794, 2023). "A study in Mantle Cell lymphoma (MCL) indicated that ZEB1 knockdown in MCL cells resulted in decreased proliferation in vitro and tumor growth in xenograft mouse models." (PMID 32309604, 2018). "ZEB1 also serves as a poor prognostic factor in mantle cell lymphoma (MCL)." (PMID 29685144, 2018). "Recent research demonstrates that salinomycin downregulates the expression of EMT activators such as zinc finger E-box binding homeobox 1 (ZEB1), resulting in suppression of the EMT in mantle cell lymphoma." (PMID 25871400, 2015).
Papillary Thyroid Cancer (9 papers, 2014 to 2025). "Silencing CD73 expression led to a reduction in ZEB1 non-coding RNA regulation reporter expression in a papillary thyroid carcinoma-derived cell line." (PMID 38388432, 2024). "In contrast, knockdown of the PI3K/AKT signaling pathway reduces the expression of N-cadherin, Twist, and Zeb1, accompanied by the expression of E-cadherin, in papillary thyroid carcinoma cell lines." (PMID 35164660, 2022). "For instance, miR-873 modulates papillary thyroid cancer progression by regulating ZEB1 expression." (PMID 41348701, 2025). "LncRNA TUG1 facilitates the development of papillary thyroid cancer via miR-145/ZEB1 axis." (PMID 32795273, 2020).
breast invasive carcinoma (8 papers, 2018 to 2024). "To examine the clinical relevance of HER2, ATF4, and ZEB1, we analyzed the expression of these genes in invasive breast carcinoma using TCGA databases." (PMID 31064130, 2019). "Taken together, we observed decreased expression of epithelial markers (E-cadherin and Desmoplakin) and found increased expression of mesenchymal markers (N-cadherin, Zeb1, Snail, Slug and Vimentin) along with an increased expression of hTERT in invasive breast cancers." (PMID 29907642, 2018). "Supporting these results, the RNA expression levels of ZEB1 and ZCCHC24 in the Cancer Genome Atlas Breast Invasive Carcinoma (TCGA-BRCA) dataset (1178 samples) were strongly correlated." (PMID 39420119, 2024). "Actually, simultaneous deregulation of miR200cand miR-30c could significantly reduce the survivalrate of breast invasive carcinoma cells via up-regulationof OCT4, SOX2, c-MYC, SNAI1, ZEB1, CDH2 and down-regulation of CDH1 (P=0.02)." (PMID 31376329, 2020). "Actually, deregulation of miR‐204, miR‐200c, miR‐34a, and miR‐10b simultaneously could significantly reduce the survival rate of breast invasive carcinoma via up‐regulation of OCT4, SOX2, KLF4, c‐MYC, NOTCH1, SNAI1, ZEB1, and CDH2 and down‐regulation of CDH1." (PMID 30710426, 2019).
corneal dystrophy (8 papers, 2013 to 2024). The term corneal dystrophy embraces a heterogeneous group of bilateral genetically determined non-inflammatory corneal diseases that are usually restricted to the cornea. "Specifically, HM was identified in six children with retinal dystrophies (RPGR; N = 2, CACNA1F; N = 2, RP2, NDP) and one child each of corneal dystrophy (ZEB1) and Stickler syndrome (causative variant in the COL9A2 gene)." (PMID 39495751, 2024). "Two cases of new pleomorphic corneal dystrophy caused by de novo mutation of ZEB1 have been reported, showing congenital corneal endothelial edema." (PMID 33923743, 2021). "Although spontaneous mutations are therefore implicated in 12% (3/25) of probands with PPCD with ZEB1 mutations, these mutations have been identified in only one other gene associated with a corneal dystrophy, the transforming growth factor, beta-induced (TGFBI) gene." (PMID 23559851, 2013). "Other candidates genes include transforming growth factor beta-induced (TGFBI) or zinc-finger E-box binding homeobox 1 (ZEB1), involved in corneal dystrophies or COL4A1, COL4A2, COL4A2, and COL4A1, encoding collagen proteins responsible for the proper function of the cornea." (PMID 32879808, 2020).
diabetic nephropathy (8 papers, 2021 to 2025). "Additionally, berberine suppressed EMT by inhibiting Snail and ZEB1 expression in tumor-associated fibroblasts and reversed renal tubular EMT by upregulating E-cadherin in diabetic nephropathy." (PMID 40525842, 2025). "In diabetic nephropathy, KMT2A regulates the H3K4me3 modification of the ZEB1 gene promoter in renal tubular epithelial cells, activating its expression." (PMID 39888275, 2025). "It is reported that ZEB1 is an essential factor with prognostic value in ESCC progression, and miR-27b-3p is a direct target of ZEB1 in diabetic nephropathy." (PMID 35865464, 2022).
head and neck squamous cell carcinoma (8 papers, 2019 to 2025). A squamous cell carcinoma that arises from any of the following anatomic sites: lip and oral cavity, nasal cavity, paranasal sinuses, pharynx, larynx, and salivary glands. "Marie-Nicole once reported that 7 days after PDT treatment for head and neck squamous cell carcinoma, ZEB1 in the exosomes of patients was downregulated to maintain the tumor cell epithelial phenotype and avoid metastasis." (PMID 34712611, 2021). "Firstly, similarly to squamous cell carcinoma of the head and neck, ZEB1 and ZEB2 could be co-expressed and regulated together." (PMID 35565409, 2022). "ZEB2 has a highly similar conformation to ZEB1, but its role in head and neck squamous cell carcinoma (HNSCC) cells is not fully understood." (PMID 39362647, 2024). "Exosomes from the plasma of head and neck squamous cell carcinoma (HNSCC) patients treated with photodynamic therapy (PDT) downregulated the expression of SLUG and ZEB1." (PMID 32252322, 2020).
metastatic cancer (8 papers, 2015 to 2025). A carcinoma which has spread from the original site of growth to another anatomic site. "Based on the HNSCC samples, the high expression of ZEB1 and ZEB2 was associated with advanced and metastatic cancer, and high levels of ZEB1 and ZEB2 predicted poor outcome." (PMID 30755200, 2019). "Transcriptional repressors for epithelial marker proteins, Zeb1/2 and snail, are frequently detected in metastatic cancer cells and are known to be involved in EMT." (PMID 26359358, 2015). "On the other hand, depletion of p66Shc in metastatic cancer cells increases the expression of ZEB1, leading to the reduced p66Shc transcription level and disruption of cell–cell contacts." (PMID 25837484, 2015). "Interestingly, we found that the expression levels of CDH1, which encodes the epithelial marker E-cadherin, CDH5, encoding vascular endothelial cadherin, and the epithelial-to-mesenchymal transition-transcription factor ZEB1, effectively distinguished primary from metastatic cancer cells." (PMID 40332096, 2025). "Results revealed a higher Mesenchymal markers in primary cancer cells (e.g., NCAM1, LAMB1, SERPINE1, TCF4, VIM, ZEB1, and ZEB2) and a higher Epithelial markers in metastatic cancer cells (e.g., CDH1, CLDN4, ELF3, EPCAM, KRT18, KRT7, and KRT8)." (PMID 37202394, 2023). "Confirming this point, studies showed that suppression of transcription factors, such as Snail or ZEB1, results in the inhibition of EMT and induction of chemoimmunosensitization in metastatic cancer cells 46-48." (PMID 33162818, 2020).
osteoporosis (8 papers, 2020 to 2024). A condition of reduced bone mass, with decreased cortical thickness and a decrease in the number and size of the trabeculae of cancellous bone (but normal chemical composition), resulting in increased fracture incidence. "E3 ubiquitin ligase CUL4A promoted osteoclast differentiation and osteoporosis by upregulating ZEB1 to repress miR-340-5p expression, causing HMGB1 upregulation and the TLR4 activation." (PMID 38504994, 2024). "The zinc-finger transcription factor ZEB1 is expressed at a low level in the skeletal endothelium of patients with osteoporosis and mouse models of that disease." (PMID 36864020, 2023). "In vitro knockdown of Zeb1 in MSCs resulted in enhanced osteogenesis, while in vivo osteoblast knockdown of Zeb1 increased bone mass in the ovariectomized mouse model of osteoporosis." (PMID 37600794, 2023). "The ZEB1 gene plays a very important role in the occurrence and development of osteoporosis." (PMID 39830009, 2023). "Second, ultrasound-triggered injectable hydrogel introduced ZEB1 gene plasmid into endothelial cell genome through Lip-ZEB1 sustained release, and then acted on the ZEB1/Notch signal pathway of cells, promoting angiogenesis and local bone reconstruction of osteoporosis through genetic engineering." (PMID 39830009, 2023). "In addition, ZEB1 expression in endothelial cells was significantly decreased in osteoporosis models." (PMID 39830009, 2023). "Our data suggested that ZEB1 could be a pathogenic factor of PMOP and a potential therapeutic target for osteoporosis." (PMID 34109218, 2021). "Based on these findings, we decided to determine whether pharmacological administration of exogenously expressed ZEB1 could ameliorate osteoporosis using a DNA-loaded cationic liposome vehicle and an OVX mouse model." (PMID 31974363, 2020). "As our in vivo study showed, ZEB1 could be a strong potential candidate for osteoporosis therapy." (PMID 34109218, 2021). "Thus, ZEB1 could be a valuable therapeutic target for osteoporosis and other bone disorders induced by damaged osteogenesis." (PMID 34109218, 2021).
tongue cancer (8 papers, 2015 to 2023). A malignant neoplasm affecting the tongue. "Knockdown of CA9 abolished the chemoresistance resulting from ZEB1 overexpression and prevented maintenance of pHi mediated by overexpression of ZEB1 in tongue cancer cells." (PMID 32299152, 2020). "For instance, ZEB1 induces CDDP resistance in tongue cancer cells by transcriptionally activating carbonic anhydrase 9 (CA9)." (PMID 29849953, 2018). "In contrast, CA9 protein was strongly expressed in only 8 of 43 tongue cancer tissues that exhibited low ZEB1 protein expression." (PMID 25890268, 2015). "Given the role of CA9 in drug resistance and that ZEB1 regulates the expression of CA9, we further investigated the role of ZEB1 in the drug resistance of tongue cancer cells." (PMID 25890268, 2015). "We found that ectopic expression of ZEB1 in tongue cancer cells significantly enhanced their resistance to chemotherapy while knockdown of ZEB1, conversely, increased sensitivity to chemotherapy." (PMID 25890268, 2015). "We have previously shown that CA9 is involved in drug resistance in tongue cancer cells, and have shown here that ZEB1 positively regulates CA9 expression." (PMID 25890268, 2015). "The literature reports mutations or deregulations in the EGF receptor, glutathione S transferase (GST), tongue cancer chemotherapy-resistance-associated protein 1 (TCRP1), and zinc finger E-box binding homeobox 1 (ZEB1) as potential contributors to chemotherapy resistance." (PMID 38136426, 2023). "Importantly, a positive correlation was observed between ZEB1 and CA9 protein expression in tongue cancer tissues, and expression of these proteins associated with a poor prognosis for patients." (PMID 25890268, 2015). "Notably, CA9 protein was strongly expressed in 39 of 41 tongue cancer tissues that exhibited high ZEB1 protein expression." (PMID 25890268, 2015). "ZEB1 bound to the promoter of CA9 to positively regulate CA9 expression in tongue cancer cells." (PMID 25890268, 2015). "Next, we wished to determine whether ZEB1 modulates chemosensitivity in tongue cancer and whether it exerts its effect via regulating CA9 expression." (PMID 25890268, 2015). "ZEB1 expression was also found to promote CA9 expression in tongue cancer cells." (PMID 25890268, 2015). "Therefore, ZEB1 transcriptionally regulates CA9 expression to mediate chemoresistance in tongue cancer via modulating pHi in response to chemotherapy." (PMID 25890268, 2015). "Importantly, tongue cancer patients with high ZEB1 expression have a poor prognosis for overall survival compared to patients with low ZEB1 expression." (PMID 25890268, 2015). "We now show here that ZEB1 predominantly correlates with drug resistance, mainly via modulating CA9 expression in tongue cancer cells." (PMID 25890268, 2015). "All the results denoted a potential correlation between ZEB1 and CA9 expression and their indication for the poor prognosis in human tongue cancer patients." (PMID 25890268, 2015). "Moreover, tongue cancer patients with both high ZEB1 and CA9 expression have worse overall survival compared to patients with both low ZEB1 and CA9 expression." (PMID 25890268, 2015).
adenoma (7 papers, 2015 to 2024). A neoplasm arising from the epithelium. "Mutation or knockdown of Zeb1 in the lung blocked the production of these Zeb1hi, CD44hi cancer-generating cluster cells from adenoma cells, in turn inhibiting cancer cell formation." (PMID 29930325, 2018). "Disruption of this loop by mutation or knockdown of Zeb1 eliminates CGC formation from adenoma cells, thereby inhibiting cancer cell production." (PMID 29930325, 2018). "Mutation or knockdown of Zeb1 in the lung blocked the production of CD44hi, Zeb1hi cancer-generating cells from adenoma cells." (PMID 29930325, 2018). "We did not detect Numb in Zeb1− adenoma cells, but it was induced with Zeb1 in mitotic adenoma cells giving rise to IC, and it co-localized asymmetrically with E-cadherin in the parental “adenoma-like” pole of these dividing cells." (PMID 29930325, 2018). "Can the removal of these factors, e.g., Snail1 or ZEB1 or combinations, revert aggressive tumor cells to a less malignant, adenoma-like phenotypic state?" (PMID 30463358, 2018). "In situ hybridization showed that miR-200 is expressed in AAH, adenomas, and surrounding normal lung, but it was repressed with Zeb1 induction in clusters." (PMID 29930325, 2018). "Expression of miR-205, ZEB1 and WAVE3 was beyond the limit of detection in all groups, i.e., normal mucosa, adenoma, CRC N0 and CRC N+." (PMID 31623346, 2019). "In hypoxic, Tgf-β1-rich interiors of adenomas, we show that adenoma cells divide asymmetrically to produce cancer-generating cells highlighted by epithelial mesenchymal transition and a CD44/Zeb1 loop." (PMID 29930325, 2018). "Nuclear Yap1 was not evident in AAH, adenomas, or surrounding normal lung, but nuclear translocation occurred specifically in hypoxic clusters where a Zeb2-to-Zeb1 switch occurs in a Tgf-β1-rich environment." (PMID 29930325, 2018). "We found an evidence that a positive CD44/Zeb1 loop is initiated in small clusters of cells derived from asymmetrically dividing adenoma cells at sites of hypoxia, EMT, and Tgf-β1 accumulation in the interiors of expanding adenomas." (PMID 29930325, 2018). "We concluded that a threshold of Zeb1 induction is necessary to drive adenoma cells to produce CGC, and in the absence of CGC, initial cancer cells are not generated." (PMID 29930325, 2018). "CGC arise at hypoxic sites in expanding adenomas and are marked by EMT and a CD44/Zeb1 loop." (PMID 29930325, 2018). "Neither Ets1 nor Zeb1 were expressed in precancerous AAH or adenomas, but both were expressed at the invasive edge of adenocarcinomas (results not shown)." (PMID 25880398, 2015). "As opposed to Zeb1, we found immunostaining for Zeb2 in AAH, adenomas, and normal lung, and it was downregulated with Zeb1 induction in hypoxic cell clusters forming in the interior of adenomas." (PMID 29930325, 2018).
colon adenocarcinoma (7 papers, 2018 to 2024). "We then used the GEPIA online analysis tool to analyze the correlation between predicated transcription factors and ZEB1 expression in the TCGA database for colon adenocarcinoma (COAD)." (PMID 32210086, 2020). "Upon identification of a homogenous downregulated profile for miR-205-5p in colon adenocarcinoma patients, functional studies demonstrated that experimental upregulation of this sequence is able to significantly raise the levels of E-cadherin through direct inhibition of ZEB1." (PMID 29352232, 2018).